S100A9 (S100 calcium binding protein A9)
Diseases named in the same sentence as S100A9 in open-access papers (continued):
Sharing a sentence is not in itself a finding about the gene and the disease.
tumor (continued). "MMP-3, S100a8, S100a9 and Pthlh transcripts were all upregulated significantly in isolated primary tumour cells of the metastatic variants in both pairs, reflecting the deregulation observed in whole tumours." (PMID 25633981, 2015). "In conclusion, this data demonstrates that expression of S100A8 and S100A9 in tumor cells is associated with differentiation, Dukes stage and lymph node metastasis in CRC." (PMID 23637971, 2013). "S100A8 and S100A9, two members of the S100 protein family, have been reported in association with the tumor cell differentiation and tumor progression." (PMID 23637971, 2013). "NSCLC patients with an overexpression of S100A9 are usually associated with poorly differentiated tumours, lower 5-year survival rate, and higher rate of relapse." (PMID 26464846, 2013). "Here, we investigated the clinical significances of S100A8 and S100A9 in tumor cells of CRC and their underlying molecular mechanisms." (PMID 23637971, 2013). "Recently, the over-expression of S100A8 and S100A9 has been observed in many tumor cells, and is associated with poor cell differentiation in some cancers of glandular cell origin." (PMID 23637971, 2013). "Gradual decrease of S100A9-positive inflammatory cell count in cancer tissues was associated with the increase of tumor pathological stage from I to IV (Wilcoxon rank sum test for 4 stages, P = 0.0265)." (PMID 22838504, 2012). "Meanwhile, S100A9 had some association with macrophages M2, suggesting that S100A9 actively promoted the intertwining of immune escape and inflammatory response in the tumor microenvironment." (PMID 40535567, 2025). "Additionally, neutrophils gather in premetastatic niches via CXCR2 or CXCR4-dependent mechanism and release oncostatin M, elastase, and S100A8/S100A9, which causes tumor cell proliferation." (PMID 40016853, 2025). "Interestingly, we observed that S100A9 depletion caused an increase in tumor cell autophagy, a cellular process associated with cancer cell death." (PMID 41173834, 2025). "Generation of a S100A9-overexpressing CT26 tumor cell line or treatment with an oncolytic virus encoding S100A9 could provide continuous release of alarmin at the tumor site and allow investigation of the anti-tumor potential of this signal." (PMID 39497822, 2024). "Furthermore, S100A8 and S100A9 can activate inflammatory cells through neutrophil chemotaxis and are strongly associated with various tumor diseases." (PMID 37580334, 2023). "Using the Single-Sample Gene Set Enrichment Analysis algorithm and immunofluorescence staining of tumor tissue sections, we found that S100A9 may be associated with macrophages." (PMID 37133437, 2023). "Plasma EV-derived S100A9 reflects tissue immune status and could serve as a surrogate marker for tumour-associated macrophages." (PMID 39516397, 2023). "Our study demonstrates that S100a9 may inhibit MDS-associated tumor escape via PD-1/PD-L1 blockade through PI3K/AKT/mTOR signaling pathway activation." (PMID 36810783, 2023). "Similarly, S100A8 and S100A9 are also linked to anticancer properties, tumor progression, and the development of tumor metastasis." (PMID 35805957, 2022). "The authors suggested that this finding may be related to the potential role of S100-A9 as an amplifier of inflammation-associated tumour development." (PMID 35409074, 2022). "Evidence from pre-clinical and clinical investigation have established S100A8 and its cognate-binding partner S100A9 as a potential prognostic biomarkers for reactivation of dormant tumor cells, prediction of metastatic risk and therapeutic responses failure in several malignancies, including BC." (PMID 35655319, 2022). "In support of this hypothesis, treatment with tasqinimod has been shown to inhibit tumor growth in a mouse model of prostate cancer in a manner that mimics the phenotype seen in S100A9 deficient mice." (PMID 35454108, 2022).
tumor (continued). "This is consistent with the reduced expression of many of the known genes that contribute to M-MDSC-suppressive function as identified in our scRNAseq dataset, including S100a8, S100a9, Ccl22 and Bcl2a1a which decreased in tumor M-MDSCs in ILC2-deficient settings." (PMID 35658010, 2022). "The protein complex S100A8/S100A9 has been associated with poor tumor prognosis." (PMID 33401528, 2021). "High expression of S100A8 and S100A9 is strongly linked to tumor promotion." (PMID 34148033, 2021). "Moreover, high expression of S100A9 in tumor stroma was associated with advanced stage, poor response rate and early recurrence." (PMID 34045609, 2021). "Additionally, S100A7, S100A8, and S100A9 recruit tumor-associated macrophages (TAM) to promote a microenvironment for immune evasion." (PMID 32728097, 2020). "We firstly showed that CCL5-deficiency in the tumor microenvironment could significantly downregulate the expression level of S100a9 in CD11bhiS100a9hi TAMs in CRC." (PMID 29991744, 2018). "Taken together, the association of blood S100A9+ MDSCs with treatment response to EGFR-TKIs might be through an interaction with tumor cells by themselves and their derived macrophages." (PMID 29484139, 2018). "Secreted S100A8/S100A9 proteins have also been implicated in cancer growth and in the establishment of a favourable environment for metastasis by promoting the migration of monocytes and tumor cells to metastatic sites." (PMID 30558665, 2018). "Moreover, mice deficient for S100A9 generated potent tumor rejection responses, while S100A9 overexpression led to accumulation of MDSC and reduced numbers of differentiated dendritic cells and macrophages." (PMID 29312298, 2017). "RAGE and TLR4 are both implicated in S100A9-mediated tumor-associated pathological effects." (PMID 27020242, 2016). "S100A9 which shares a lot of similar characteristics with other S100 proteins locates on a cluster of human chromosome 1q21, where several chromosomal abnormalities have been found to be linked with neoplasia." (PMID 27020242, 2016). "S100A9 is a calcium binding protein implicated in tumor growth." (PMID 27021626, 2016). "This points to an important role that S100A9 plays in maintaining the differentiated state of epithelium and suggests that its downregulation may be associated with increased susceptibility to tumor formation." (PMID 26788548, 2015). "This suggests the important role that S100A9 plays in maintaining the differentiated state of epithelium and suggests that its downregulation may be associated with increased susceptibility to tumor formation." (PMID 26788548, 2015). "S100A8 and S100A9, two members of the S100 family of calcium binding proteins, are abundantly produced during acute and chronic inflammation and play an important role in inflammation associated tumor development." (PMID 22359662, 2012). "Immunohistochemical staining revealed S100A9 in tumor-associated inflammatory cells." (PMID 22838504, 2012). "In addition to other proposed functions, S100-A9 promotes NF-κB activation and has been associated with tumor development, cancer invasion or metastasis." (PMID 21760917, 2011). "The group I over expressed genes have members of keratin family and S100A9 these genes are required in the maintenance of cellular damage and are highly produced when the cell is under stress conditions this can be the cause of over expression of these genes in tumor tissues." (PMID 39140365, 2024). "Therefore, we concluded that S100a9 may inhibit MDS-associated tumor escape via PD-1/PD-L1 blockade through PI3K/Akt/mTOR signaling pathway activation." (PMID 36810783, 2023). "In studies of malignant solid tumors, such as CRC, breast cancer, and prostate cancer, S100A8 and S100A9 levels have been found to be elevated in tumor tissues compared with normal and benign tissues, and their increased expression has been associated with tumor aggressiveness and metastasis." (PMID 36510315, 2022).
tumor (continued). "Thus, assessing S100A9 and MDSCs in tumor tissue and also peripheral blood could help as a diagnostic marker of CRC progression." (PMID 33117687, 2020). "Over the past few decades, increasing experimental evidence has demonstrated that either S100A9 or MDSCs contribute to tumor development, suggesting that the detection of S100A9 and/or MDSCs in peripheral blood may be a diagnostic and progression prediction marker for CRC." (PMID 31620141, 2019). "S100A9 (myeloid-related protein 14), implicated in the abnormal differentiation of myeloid cells in the cancer stroma, contributes to create an immunosuppressive microenvironment that inhibits the generation of a protective cellular immune response by the tumor-bearing host." (PMID 29344558, 2017). "In silico screening identified S100a9 as one of the most highly upregulated inflammation-related genes in aged livers, which was confirmed in both tumor-naïve and metastatic liver tissues." (PMID 42192994, 2026). "Forming a common heterodimer structure, S100A8 and S100A9 have been widely reported to participate in multiple biological processes in tumor cells." (PMID 41513624, 2026). "Alternatively, neutrophil-derived MMP9, as well as S100A8 and S100A9, influences tumor cell survival at the metastasizing site." (PMID 39653768, 2025). "Nonetheless, our results demonstrate that inhibiting S100A9 in tumor cells either by genetic means or using an S100A9 inhibitor significantly impedes the recruitment of immunosuppressive granulocytic MDSCs in the tumor." (PMID 41173834, 2025). "S100A8 and S100A9, small‐molecule calcium‐binding proteins, play pivotal roles in tumor progression." (PMID 40452814, 2025). "Our study suggests that S100A9 suppresses the anti-tumor immune responses by enhancing the enrichment of granulocytic MDSCs and reducing the recruitment and activation of cytotoxic T cells within SCLC tumors." (PMID 41173834, 2025). "Using the KP1 subcutaneous tumor model, we observed that S100A9 inhibition alone or in combination with cisplatin demonstrated a significant survival advantage over cisplatin or tasquinimod administration alone." (PMID 41173834, 2025). "Quantitative proteomics (iTRAQ) and mRNA analyses revealed that S100A9 levels rise in parallel with tumor stage, implicating its involvement in the transition from localized to more advanced disease." (PMID 41009692, 2025). "S100A9, a key mediator of tumor invasion and metastasis, enhances tumor cell migration and invasiveness." (PMID 41409248, 2025). "S100 proteins, particularly S100A8 and S100A9, have been shown to modulate the tumor microenvironment in ways that promote neovascularization, thereby supporting tumor expansion and metastasis." (PMID 41404073, 2025). "S100a8, S100a9, and the S100a8/a9 heterodimer are involved in cancer development, progression, and metastasis by interfering with tumor metabolism and microenvironment." (PMID 39796176, 2025). "We found that tumor development was markedly slower in S100A9 downregulated tumors compared to their respective controls." (PMID 41173834, 2025). "S100 family members such as S100A8, S100A9, S100A13, and S100A6 are upregulated in advanced BC and are associated with tumor progression, immune suppression, and poor prognosis." (PMID 41404073, 2025). "L1, also known as calprotectin, is a heterodimer composed by two calcium-binding proteins S100A8 and S100A9, whose upregulation was reported in different cancers, increasing tumor growth, invasion and metastasis." (PMID 40146757, 2025). "Neutrophils can be recruited by chemoattractants, such as CXCL8/IL-8, CXCL12/SDF-1, VEGF, S100A8, and S100A9, secreted both from the primary tumor and from stroma cells in the PMN." (PMID 40370456, 2025). "In contrast, other S100 proteins such as S100A6, S100A8, S100A9, and S100A11 are frequently upregulated in various malignancies, including BC, where they are linked to tumor-promoting functions." (PMID 41404073, 2025).
tumor (continued). "S100A8 and S100A9, for instance, activate the MAPK and NF-κB pathways, which in turn promote cytokine production, leukocyte recruitment, and tumor-associated inflammation." (PMID 41404073, 2025). "We discovered that in tumor cells, autocrine S100A9/RAGE signaling regulates the expression of MAGE-A3, inhibiting autophagy and increasing cell survival." (PMID 41173834, 2025). "Mechanistically, our results suggest that tumor cell-secreted S100A9 binds to RAGE in an autocrine manner and regulates the activation of Akt/GSK3α/β/Snail for increasing cell survival and migration." (PMID 41173834, 2025). "For example, antibodies against S100A9 suppressed tumor growth in prostate cancer models by modulating the immune microenvironment." (PMID 41404073, 2025). "Granulocytic MDSCs enhance CRC cell pluripotency by transferring exosomal S100A9 proteins to tumor cells." (PMID 41010517, 2025). "For instance, S100A9 is highly expressed in neutrophils and monocytes and acts as a promoter by regulating tumor metabolism and the immune microenvironment, thereby facilitating tumor growth and metastasis." (PMID 40296873, 2025). "This overexpression correlates with enhanced tumor cell proliferation, migration, and invasion, suggesting that S100A9 contributes significantly to the aggressive phenotype observed in MIBC." (PMID 41009692, 2025). "S100A9 depletion or pharmacological inhibition using tasquinimod reduced tumor growth and metastasis in vivo." (PMID 41173834, 2025). "The cellular density of S100A9-expressing immune cells in the HCC tumor core in four tested HCC patients was significantly increased compared to healthy control samples." (PMID 40352930, 2025). "Cancer-associated fibroblasts (CAFs) respond to extracellular S100A4, S100A8, and S100A9 by activating pro-inflammatory and pro-fibrotic signaling pathways, which enhance extracellular matrix remodeling and facilitate tumor invasion." (PMID 41404073, 2025). "In Mass’s study, infiltrating CXCR4+ neutrophils was identified as the primary source of S100A9 in the tumor microenvironment." (PMID 40069854, 2025). "Possible mechanisms involve elevating intracellular S100A9 via the TLR4/NF-κB pathway in both tumor cells and macrophages, as well as initiating the IL-6/p-STAT3/c-MYC pathway through the TLR4 receptor on macrophages." (PMID 40771747, 2025). "S100A8 and S100A9, both associated with CRC progression, were elevated, consistent with studies that examined their protein expression in tumour and matched distant normal tissues using IHC and WB39." (PMID 40348885, 2025). "Further experiments demonstrated that reducing S100A9 expression impairs tumor cell proliferation and invasiveness, pointing to its viability as a therapeutic target." (PMID 41009692, 2025). "In this context, emerging candidates such as GDF-15, VEGF, TGF-β1, HSP90, HMGB1, and S100A9 have garnered considerable attention for their roles in tumor progression, angiogenesis, immune modulation, and stress response." (PMID 41009692, 2025). "IHC analysis of selected HCC patients revealed a strong infiltration of tumor stroma and parenchyma with S100A9-expressing immune cells in comparison to healthy control, as defined by an experienced pathologist." (PMID 40352930, 2025). "Except for M09, all other subtypes expressed macrophage markers such as CD68, C1QB, S100A9, and AIF1, suggesting that they are tumor-associated macrophages (TAMs)." (PMID 40260248, 2025). "In agreement with the previous results, we observed a significant decrease in tumor growth upon S100A9 depletion compared to the scramble shRNA control group." (PMID 41173834, 2025). "Based on the results obtained previously, the first objective was to validate the specific expression of S100A9 in the hypoxic and necrotic areas of the tumor." (PMID 39744679, 2025).
tumor (continued). "We also utilized different preclinical mouse models, including patient-derived xenograft (PDX) mouse models, to evaluate the effects of tasquinimod, a drug that inhibits S100A9 and can reduce the pro-tumor effects of S100A9." (PMID 41173834, 2025). "For example, S100A9 contribute to promoting tumor growth in hepatocellular carcinoma by phosphorylation of ERK1/2 and P38 via binding to RAGE receptor." (PMID 41009692, 2025). "These proteins also interact with the tumor immune microenvironment, with S100A8 and S100A9 being associated with immune infiltration and inflammatory pathways." (PMID 41303754, 2025). "Multiplex immunofluorescence accordingly revealed that primary tumor tissues from mice treated with combination ICT showed a significant increase in tumor cells co-expressing GFP (marker of tumor cells) and myeloid markers such as S100A9, CD68, and F4/80." (PMID 41290625, 2025). "Simultaneously, S100A8/S100A9 activation facilitates leukocyte recruitment, angiogenesis, and tumor migration, along with the enhancement of some genes, including Cxcl1, Ccl5 and Ccl7, Slc39a10, Lcn2, Zc3h12a, Enpp2 and other genes." (PMID 38361783, 2024). "To confirm their identity, firstly we performed IHC with standard immune cell markers (CD45, CD68, and CD8) and S100A9 on tumor sections, distinguishing tumor core and necrotic areas." (PMID 38411438, 2024). "Another interesting functional network concerned the “migration and chemotaxis of neutrophils and myeloid leukocytes” and involved proteins more abundant in S tumor samples, such as S100A9, S100A8, and platelet basic protein (PBP)." (PMID 39195201, 2024). "It was found that S100A9 was mainly expressed in monocytes and macrophages, and only a small amount was expressed in tumor malignant cells." (PMID 39137310, 2024). "Increased levels of S100A9 were found in plasma in many cancer patients, and some studies have showed correlations between S100A9 levels and tumor progression or resistance to checkpoint inhibition." (PMID 39497822, 2024). "On the contrary, after treatment of S100A8/S100A9 in some tumor cells, it can induce cell death through apoptosis and autophagy, and this process would be rectified using N-acetyl-L-cysteine (NAC) through decreasing mitochondria reactive oxygen species (ROS)." (PMID 38361783, 2024). "Taken together, these findings confirm an early anti-tumor effect of S100A9 in this mouse tumor model." (PMID 39497822, 2024). "Stromal S100A9 localization correlates to parameters such as large tumor size, HER2 positivity and nodal stage in ER-negative/PR-negative breast cancers." (PMID 39830522, 2024). "Previous research on S100A9 in tumors focused on immune-related cells and paracrine function while ignoring the effect of S100A9 on tumor cells themselves." (PMID 39137310, 2024). "We observed that Paquinimod treatment and intratumor injection of recombinant S100A9 have opposite anti-tumor effects." (PMID 39497822, 2024). "The DC3 subpopulation, notable for CD14 and S100A9 markers, included 765 cells enriched within tumor samples." (PMID 38972873, 2024). "Tasquinimod (oral treatment, day 0 or 1 to end of experiment), q-compound targeting TLR4 signaling of S100A9, alone, with SurVaxM peptide and GM-CSF or with tumor-targeted superantigen." (PMID 39497822, 2024). "It has also been shown that S100A8/A9, S100A9, and S100A8 have the potential to be tumor diagnostic or prognostic biomarkers." (PMID 39594999, 2024). "We postulated that HSP90, HMGB1, and S100A9 have the potential to be predictive biomarkers for supporting tumor metastasis categorization using histopathology." (PMID 39768997, 2024). "We demonstrate that blocking S100A9 signaling using Paquinimod is detrimental to the initiation of anti-tumor responses in mice models of cancer." (PMID 39497822, 2024). "Intratumoral injection of recombinant S100A9 early after mice inoculation with CT26 cells had an anti-tumor effect." (PMID 39497822, 2024).